IL1A (interleukin 1 alpha)
Diseases named in the same sentence as IL1A in open-access papers (continued):
Sharing a sentence is not in itself a finding about the gene and the disease.
lung fibrosis (continued). "Here, we found that IL-1α and TGF-β were higher in patients with signs of lung fibrosis compared to IFN-β in PC patients." (PMID 34944747, 2021). "Increased levels of IL-1β and IL-1α have been described to be involved in the pathogenesis of ARDS and subsequent pulmonary fibrosis." (PMID 26303896, 2015). "Thus, we consider that AIM2 activation that leads to IL-1α, IFN-α and TGF-β release is likely to be involved in the establishment of lung fibrosis in PC syndrome." (PMID 35844548, 2022). "Collectively, these results similarly to what we observed for IL-1α, suggest that there is an inflammasome-independent function of the AIM2 receptor that correlates with higher levels of the pro-fibrotic TGF-β from PBMCs from PC patients with signs of lung fibrosis." (PMID 35844548, 2022). "Similarly, in our previous work, we found that IL-1α was responsible for TGF-β release from idiopathic pulmonary fibrosis (IPF)-derived PBMCs in a caspase-4-, but not caspase-1-, dependent manner." (PMID 30930781, 2019).
cervical carcinoma (17 papers, 2013 to 2025). A carcinoma arising from either the exocervical squamous epithelium or the endocervical glandular epithelium. "It is noteworthy that SNP rs3783553 of IL1A increased the risk of cervical carcinoma by eliminating targeting points of miR-122." (PMID 32047552, 2020). "Atopobiaceae (CST IV) were enriched in cLSIL, cHSIL, and cervical carcinoma and positively correlated with IL-1α, IL-4, IL-10, IL-12, IL-36γ, IFN-α2, IFN-γ, and TNF-α in cervicovaginal lavages." (PMID 40362199, 2025). "Some research argued that IL1A and IL1B were associated with tumor progression and prognosis; in addition, IL-1A was an independent predictor of survival in cervical cancer patients." (PMID 36253777, 2022). "In human papilloma virus (HPV)-induced cervical cancer cells, IL-1α was found to act as an adjuvant by activating dendritic cells for anti-tumor effects." (PMID 33430381, 2021). "Necroptotic cervical cancer cells produce IL-1α, which was essential for activating DCs to release IL-12, which is a cytokine crucial for antitumor activities." (PMID 31122251, 2019). "Our study provides clear evidence that in the context of PolyIC stimulation, IL-1α release from cervical cancer cells can potentiate IL-12 production by DC." (PMID 25888634, 2015). "In summary, our study has identified a novel RIPK3- and IL-1α-dependent mechanism that links dsRNA treatment of cervical cancer cells with DC activation." (PMID 25888634, 2015). "We demonstrated that the release of the alarmin IL-1α during PolyIC-induced necroptosis in cervical cancer cells was necessary for an effective IL-12 response." (PMID 25888634, 2015). "We unraveled the kinase RIPK3 as the critical determinant for IL-1α release and for the DC-stimulatory capacity of PolyIC-treated cervical cancer cells." (PMID 25888634, 2015). "A striking finding of our study was that PolyIC-mediated IL-1α release from cervical cancer cells is required in order to enhance IL-12 production by DC." (PMID 25888634, 2015). "It is therefore probable that expression of IL-1α in cervical cancers can act via similar manner to confer virulent tumor phenotype and poorer prognosis in these patients." (PMID 25237386, 2014). "Expressed IL-1α can then stimulate cervical cancer cell migration to adjacent structures within the pelvis and perineum, hence conferring poor prognosis." (PMID 25237386, 2014). "Here we investigated the expression of IL-1α in cervical cancer, the role of SP in the regulation of IL-1α in neoplastic cervical epithelial cells and the molecular mechanism underlying this regulation." (PMID 25237386, 2014). "One of its targets, IL1A, was also shown upregulated in cervical carcinoma." (PMID 34638231, 2021). "IL-1 (both IL-1α and -β) is the other interleukin present in higher levels in cervical cancer." (PMID 29854832, 2018). "EP2 and its signaling have been found to be up-regulated in cervical cancer and its role in the induction of IL-1α in cervical cancer could explain the greater expression of IL-1α in cervical cancer tissue explant relative to normal cervical tissue." (PMID 25237386, 2014). "The SP-mediated induction of a pleotropic pro-inflammatory cytokine IL-1α in normal and neoplastic cervical epithelial cells suggests that SP may promote cervical inflammation as well as progression of cervical cancer in sexually active women." (PMID 25237386, 2014). "In addition, these data suggests a similar pattern of IL-1α expression in cervical cancer as demonstrated in other malignancies." (PMID 25237386, 2014). "Data presented confirmed the elevated expression of IL-1α in cervical cancer." (PMID 25237386, 2014). "SP-mediated induction of IL-1α in normal and neoplastic cervical epithelial cells suggests that SP may promote cervical inflammation as well as progression of cervical cancer in sexually active women." (PMID 25237386, 2014).
cervical carcinoma (continued). "Moreover, while still transcribed in immortalized keratinocytes, the same transcriptional down-regulation was also detected in cervical carcinoma cells when other cytokines such as IL-1α, IL-18 and IL-33 were monitored by q-PCR." (PMID 23935506, 2013). "Hence, the authors used viral dsRNA (polyIC) to induce RIPK3-dependent necroptosis in cervical cancer cells, resulting in the release of intracellular IL-1α, which could then activate dendritic cells to produce IL-12 and mount an anti-tumor response." (PMID 33430381, 2021). "Another study found an increase in IL-1α expression in cervical cancer compared to adjacent non-tumor tissue using IHC." (PMID 39727946, 2024). "Given that IL1A is produced by tumor cells, it stimulates the proliferation of cervical cancer cells but not normal cervical cells." (PMID 34203721, 2021). "In contrast to the high levels of immunoreactive IL-1α observed in cervical cancer tissue, little or no staining for IL-1α was observed in the normal cervical tissues." (PMID 25237386, 2014).
head and neck squamous cell carcinoma (17 papers, 2015 to 2026). A squamous cell carcinoma that arises from any of the following anatomic sites: lip and oral cavity, nasal cavity, paranasal sinuses, pharynx, larynx, and salivary glands. "Moreover, IL-1α expression was significantly associated with distant metastasis and poor patient survival in head and neck squamous cell carcinomas." (PMID 37835389, 2023). "Notably, increased IL-1α production in tumors has been associated with increased metastases and poor survival of patients with head and neck squamous cell carcinomas." (PMID 36426368, 2022). "High tumor expression of the cytokine interleukin-1 alpha (IL-1α) is associated with an aggressive tumor phenotype and poor clinical outcomes in head and neck squamous cell carcinoma (HNSCC)." (PMID 42013543, 2026). "IL-1α in combination with the EGFR inhibitor can induce a T cell-dependent anti-tumor immune response in head and neck squamous cell carcinomas." (PMID 34073987, 2021). "Interleukin-1 alpha (IL-1α) is a pleiotropic cytokine involved in inflammation and immune response and is upregulated in many solid tumors including head and neck squamous cell carcinomas." (PMID 31320902, 2019). "Moreover, a significant correlation between IL-1α expression and distant metastasis was found in patients with head and neck squamous cell carcinoma." (PMID 32825489, 2020). "We studied whether IL-1α expression is a prognostic marker of distant metastasis in patients with head and neck squamous cell carcinoma (HNSCC)." (PMID 26460957, 2015). "Furthermore, we chose to analyze the role of IL-1α and IL-6 due to their known implication in head and neck squamous cell carcinoma development, while IL-17 was chosen due to its known role in fibrotic changes, which often characterize oral lesions from both GVHD and LPO." (PMID 39728035, 2024). "IL‐1α‐MPs were injected intraperitonially into head and neck squamous cell carcinoma (HNSCC)‐bearing C57Bl/6 mice and monitored for changes in weight, tumor growth, circulating cytokines/chemokines, hepatic and kidney enzymes, blood pressure, heart rate, and tumor‐infiltrating immune cells." (PMID 37206237, 2023). "Head and neck squamous cell carcinoma (HNSCC) patients with distant metastasis have higher levels of IL1A than those without metastasis." (PMID 34203721, 2021).
ovarian carcinoma (17 papers, 2005 to 2025). A malignant neoplasm originating from the surface ovarian epithelium. "For example, in both breast and ovarian cancer risks are increased by the rs17561 minor allele, suggesting more IL‐1α is beneficial." (PMID 36175368, 2023). "In a very large sample size of nearly 40,000 participants, this A114S SNP in IL-1α (rs17561), was also found to be associated with a higher risk of ovarian cancer." (PMID 33430381, 2021). "However, their results failed to support an association between selected polymorphisms at IL-1α, IL-β, IL-6, IL-10, or IL-18 gene and increased risk of ovarian cancer in USA." (PMID 34582655, 2021). "Assessing IL-1β levels in the peritoneal fluid of women also showed, similar to IL-1α, statistically significant higher levels of IL-1β in the peritoneal fluid of women with ovarian cancer stage G3 vs. G1 (p<0.001) and G3 vs. G2." (PMID 41561739, 2025). "The mean value of IL-1α was observed higher (7.04±0.85 pg/ml) in ovarian cancer patients in comparison to control subjects (5.68±0.53 pg/ml)." (PMID 27902750, 2016). "The research carried out by Pollard, and Zeisleret al., reviewed the measurement of interleukin 1-alpha (IL-1α) in the serum of ovarian cancer patients and concluded that there is increase level in the ovarian cancer patients as compared to controls." (PMID 27902750, 2016). "A phase I clinical trial showed recombinant human IL-1α treatment having minor antitumor effect in advanced recurrent ovarian cancer." (PMID 21765834, 2011). "The major objective of this study was to determine the level expression of IL-1 ligands system (IL-1α, IL-1β and IL-1RA) in the most common subtypes of ovarian cancer cells compared to endometrial cells." (PMID 20181040, 2010). "This is further exemplified by the positive effect of IL-1α treatment in patients with ovarian cancer." (PMID 15870720, 2005). "Statistical analysis showed statistically significantly higher IL-1α concentrations in serum of patients with ovarian cancer stage G3 compared to patients in the reference group (p<0.001) and patients in the study group stage G1 vs. G3 (p<0.001) and G2 vs. G3 (p<0.001)." (PMID 41561739, 2025). "Interestingly, IL-1α has previously been shown to play a key role in cisplatin sensitivity in human ovarian cancer cells, whereby IL-1α was shown to enhance sensitivity to cisplatin." (PMID 30791601, 2019). "Using a more potent anti-inflammatory, another randomized controlled trial is underway, using bermekimab, which is a humanized antibody to IL-1α and examining its effects on muscles, physical function and appetite in patients with lung, pancreatic or ovarian cancer (MICA trial)." (PMID 31487957, 2019). "Similarly, the levels of various cytokines TNF-α and IL-1α were also increased in the patients of ovarian cancer (32.17±3.52 pg/ml and 7.04±0.85 pg/ml respectively)." (PMID 27902750, 2016). "The levels of IL-1α secretion were higher in endometrial cells than ovarian cancer cells." (PMID 20181040, 2010). "We have measured levels of IL-1α, IL-1β and IL-1RA in endometrial and ovarian cancer cells." (PMID 20181040, 2010). "Thus, this suggests that increased IL-1α secretion could result in increased tumorigenicity and metastasis in ovarian cancer." (PMID 33430381, 2021). "The top distinctive genes for the proliferation metaprofile include, besides previously used markers, numerous genes related to malignancy and ovarian cancer progression, in particular cytokines and their receptors: CXCL1, IL1A, CXCL8, IL1B, IL1R1, and IL1R2." (PMID 29362714, 2017). "While there is a lack of information that relates IL-1α to paclitaxel, previous works have described that paclitaxel induces the upregulation of IL-6 in ovarian cancer cells through the TLR4–NF-κB cascade." (PMID 35163066, 2022).
ovarian carcinoma (continued). "Stress variables (MDA, AGEs, AOPPs, NO), profile of antioxidants (SOD, Catalase, Vitamin E & A, GSH, GRx, GPx) and inflammatory biomarkers (MMP-9, MMP-2, MMP-11, IL-1α and TNF-α) were biochemically assessed from venous blood of fifty ovarian cancer patients and twenty healthy control subjects." (PMID 27902750, 2016). "IL-1α mRNA expression was higher in TOV-21G cells (P < 0.05), whereas no statically changes of IL-1α mRNA expression was observed between endometrial cells and the other epithelial ovarian cancer cell lines." (PMID 20181040, 2010).
Parkinson disease (17 papers, 2011 to 2025). A progressive degenerative disorder of the central nervous system characterized by loss of dopamine producing neurons in the substantia nigra and the presence of Lewy bodies in the substantia nigra and locus coeruleus. "IL-1α is the primary cytokine associated with the development of the neuroinflammatory reaction and the pathogenesis of Parkinson’s disease." (PMID 38642286, 2024). "For example, it has been demonstrated that reactive microglia, by secreting IL-1α, TNFα and C1q, induce a unique phenotype in astrocytes in neurodegenerative disorders such as Alzheimer’s and Parkinson’s disease." (PMID 39463449, 2025). "Recently, it was shown that activation of microglia leads to the conversion of resting astrocytes to reactive astrocytes via secretion of IL-1α, TNFα, and C1q in a variety of neurodegenerative disorders including AD and Parkinson’s disease (PD)." (PMID 33902708, 2021). "In murine models of neurodegenerative Parkinson’s disease, the intrathecal graft of hDPSCs ameliorated behavioral deficits and dopaminergic (DA) neuron loss, by upregulating anti-inflammatory cytokines IL2, IL4, and TNF-β and reducing IL-1α, IL- 1β, IL6, IL8, and TNF-α pro-inflammatory ones." (PMID 33805573, 2021). "Collectively, our data suggest that long-term exposure to increased IL-1β/IL-1α could evoke parkinsonism-related outcomes such as impairment in motor skills, a higher number of activated microglia, and reduced number of TH-neurons as described in IL-1ra−/− mice." (PMID 27356916, 2017). "In Parkinson’s disease patients, SATB1 (a CDKN1A inhibitor) levels are reduced in the substantia nigra, while CDKN2A, MMP3, IL-6, IL-1α, and CXCL8 levels are elevated, indicating an increased aging burden." (PMID 39963130, 2025). "Astrocytes are converted from a resting form to a reactive form by activated microglia secreting IL-1α, TNF-α, and C1q, contributing to neurodegenerative diseases like AD and Parkinson’s disease (PD)." (PMID 40474934, 2024). "Recently, it has been shown that activation of microglia leads to the conversion of normal astrocytes to reactive astrocytes via secretion of IL‐1α, TNF‐α and complement component 1 (C1q) (T/I/C) in a variety of neurodegenerative diseases including AD and Parkinson's disease." (PMID 37905690, 2024).
chronic periodontitis (16 papers, 2012 to 2025). A chronic inflammatory process that affects the tissues that surround and support the teeth. "A very recent study involving Bayesian methods to rate meta-analysis data on polymorphisms in IL-1 genes identified the IL-1A/rs1800587 and IL-1B/rs1143634 polymorphism as noteworthy biomarkers for chronic periodontitis susceptibility." (PMID 36429405, 2022).
glaucoma (16 papers, 2007 to 2026). Increased pressure in the eyeball due to obstruction of the outflow of aqueous humor. "For instance, deficiency of three proinflammatory cytokines, complement component 1, subcomponent q (C1q), interleukin 1 alpha (Il1a), and tumor necrosis factor (Tnf), resulted in significant protection of RGCs after glaucoma-relevant insults." (PMID 41728092, 2026). "NLY01, used to block the induction of inflammatory astrocytes by inhibiting the release of IL-1α, TNF-α and C1q from microglia, was successfully used in studies of PD and glaucoma-associated neurodegeneration to ameliorate disease severity." (PMID 34539348, 2021). "Using a mouse model of glaucoma, we demonstrate that ocular hypertension is sufficient to trigger production of C1q, interleukin-1α (IL-1α), and tumor necrosis factor α (TNF-α), three cytokines necessary and sufficient to drive the formation of A1 astrocytes." (PMID 33147455, 2020). "It has been reported that polymorphisms in the IL1A and IL1B genes are associated with Primary Open Angle Glaucoma (POAG)." (PMID 20565898, 2010). "Many more important gene variants have recently been associated with glaucoma risk, such as apolipoprotein E (APOE), endothelin receptor type A gene (EDNRA), IL-1α, methylenetetrahydrofolate reductase (MTHFR), and beta-adrenergic receptors." (PMID 17563722, 2007). "IL1A and TNF polymorphisms are associated with primary open angle glaucoma." (PMID 33147455, 2020). "The anti-inflammatory properties of iTRAB® were investigated in 3D-HTMCs through its ability to modulate the increase in pro-inflammatory (i.e., IL-1α, IL-1β, IL-6, and TNF-α) and pro-fibrotic cytokines, as well as MMPs which are known to be associated with glaucoma." (PMID 33172106, 2020). "However, we did detect increases in IL-1α and IL-1β, which are also elevated in glaucoma." (PMID 31354422, 2019). "Further, the regulation of NFκB and AP-1 by IL-33 and IL-1α via MYD88 has been reported in AMD, glaucoma, DR and PVR." (PMID 35269741, 2022). "Recently, activated microglia were shown to induce reactive neurotoxic astrocytes by the release of interleukin-1 alpha (IL-1α), TNFα, and the classical complement component (C1q), and consequently drive RGC degeneration in the microbead glaucoma model." (PMID 34366851, 2021). "Using the microbead-induced ocular hypertension mouse model of glaucoma, we show that microglia and infiltrating macrophages upregulate C1q, TNF-α, and IL-1α." (PMID 33147455, 2020). "Treatment with the GLP-1R agonist NLY01 reduced microglia/macrophage production of IL-1α, TNF-α, and C1q; decreased A1 astrocyte conversion; and protected against RGC death in this mouse model of glaucoma." (PMID 33147455, 2020). "Many of the cytokines with increased expression measurements in our study (IL-1α, IL-1β, IL-6, TNF-α, FasL) were already described as being elevated in glaucoma patients." (PMID 30967499, 2019). "Microglial secretion of IL-1α, TNF-α, and C1q was increased in a mouse glaucoma model, suggesting the possibility that microglia induce A1 astrocytes resulting in RGC damage in glaucoma." (PMID 38983051, 2023). "Il-1α and Il-1β mRNAs were found to be increased in the TM in glaucomatous eyes compared to controls, acting in a feedback loop to control endothelial leukocyte adhesion molecule 1 (ELAM-1), an early marker of atherosclerotic plaque that forms in glaucoma." (PMID 31379825, 2019). "Additionally, IL-1α concentrations were noted to be significantly increased in the aqueous humor of primary open-angle glaucoma with and without diabetes." (PMID 35269741, 2022). "Although IL-1α, TNF-α, and C1q have been independently implicated in glaucoma, it is not known whether they act in concert to induce A1 astrocyte reactivity in glaucomatous retinas." (PMID 33147455, 2020).
glaucoma (continued). "Here, normotensive eyes showed no upregulation of IL-1α, TNF-α, and C1q proteins, suggesting that if present, microglial reactivity in the control eye may not result in A1 astrocyte activation in this model of glaucoma." (PMID 33147455, 2020).